ZMYND11 (zinc finger MYND-type containing 11)
Description:
Chromatin reader that specifically recognizes and binds histone H3.3 trimethylated at 'Lys-36' (H3.3K36me3) and regulates RNA polymerase II elongation. Does not bind other histone H3 subtypes (H3.1 or H3.2) (By similarity). Colocalizes with highly expressed genes and functions as a transcription corepressor by modulating RNA polymerase II at the elongation stage. Binds non-specifically to dsDNA. Acts as a tumor-suppressor by repressing a transcriptional program essential for tumor cell growth. (Microbial infection) Inhibits Epstein-Barr virus EBNA2-mediated transcriptional activation and host cell proliferation, through direct interaction.
Synonyms: BRAM1; BS69; MRD30
Tractability: PROTAC: UniProt records ubiquitination sites on it; ubiquitination databases record sites on it; its protein half-life has been measured.
Gene: Protein-coding gene on chromosome 10 (130,088 to 254,638, forward strand). Ensembl gene ENSG00000015171.
Subcellular location: Nucleus; Chromosome
Subcellular location (Human Protein Atlas): Nucleoplasm
Gene Ontology:
Molecular function: double-stranded DNA binding; histone H3K36me3 reader activity; protein binding; zinc ion binding; transcription corepressor activity; DNA binding
Biological process: defense response to virus; negative regulation of canonical NF-kappaB signal transduction; negative regulation of extrinsic apoptotic signaling pathway; negative regulation of JNK cascade; negative regulation of DNA-templated transcription; regulation of signal transduction; regulation of transcription elongation by RNA polymerase II; chromatin organization
Cellular component: chromosome; nucleoplasm; nucleus
Genetic constraint (gnomAD): Loss-of-function variants: 7 observed, 79.4 expected, observed/expected ratio (o/e) 0.0882, 90% interval 0.049 to 0.17. The upper end of that interval is the gene's LOEUF score, 0.17, which puts it in group 1 of 6, group 1 being the genes least tolerant of losing a copy. Missense variants: 370 observed, 717.11 expected, observed/expected ratio (o/e) 0.52, 90% interval 0.47 to 0.56. Synonymous variants: 231 observed, 233.55 expected, observed/expected ratio (o/e) 0.99, 90% interval 0.89 to 1.1.
Gene-disease validity (ClinGen):
ClinGen rates the evidence that ZMYND11 causes each of these diseases.
syndromic complex neurodevelopmental disorder (autosomal dominant): Definitive. A disorder that involves more than one phenotype associated with the central nervous system, including but not limited to intellectual disability, autism, and seizures (epilepsy), and also a distinctive pattern of other features including dysmorphisms and/or congenital malformations.
Homologues: Orthologues: chimpanzee ZMYND11 (100% identical), macaque ZMYND11 (99% identical), rabbit ZMYND11 (99% identical), guinea pig ZMYND11 (99% identical), dog ZMYND11 (99% identical), pig ZMYND11 (99% identical), rat Zmynd11 (98% identical), mouse Zmynd11 (98% identical), tropical clawed frog zmynd11 (87% identical), zebrafish zmynd11 (74% identical), Drosophila melanogaster CG8569 (23% identical). Paralogues in human: ZMYND8 (32% identical), PHF12 (13% identical), PHF21A (8% identical), AIRE (6% identical), PHF21B (6% identical).
Diseases named in the same sentence as ZMYND11 in open-access papers:
ZMYND11 is named in the same sentence as 53 diseases in open-access papers, as found by Europe PMC text mining. Sharing a sentence is not in itself a finding about the gene and the disease. The quoted sentences say what the papers report.
developmental delay (6 papers, 2019 to 2025). "In 2020, CHD6, KLC1, and ZMYND11 were linked to early‐onset dystonia combined with developmental delay or intellectual disability." (PMID 40533913, 2025). "ZMYND11 is highly expressed in fetal brain, and ZMYND11 haploinsufficiency causes 10p15.3 deletion syndrome in human, which is featured by global developmental delay, intellectual disability, behavioral abnormalities, etc.." (PMID 40281637, 2025). "Moving onto neurological disorders in cases with ZMYND11 pathological variants, their range is immensely wide and includes generalised developmental delay, seizures, autism and behavioural abnormalities." (PMID 38397245, 2024). "ZMYND11 has been associated with neurodevelopmental disorders, global developmental delay, seizures, and hypotonia, and it is a potential causative gene in complex neurodevelopmental phenotypes." (PMID 38741036, 2024). "In another report, deletions including DIP2C and/or ZMYND11 were identified in several patients with developmental delay including three patients with seizures." (PMID 31190668, 2019). "Four genes (UCP2, UCP3, SCAPER, and TSHR) are related to the body weight (HP:0004324 and HP:0004323), and four genes (C2CD3, UCP2, ZMYND11, and TSHR) are involved in modulating the phenotype of globe developmental delay (HP:0001263)." (PMID 32973871, 2020).
Intellectual disability (6 papers, 2020 to 2025). "A recent analysis found evidence that loss-of-function of ZMYND11 resulted in intellectual disability, hypotonia, dysmorphic features, and feeding difficulties." (PMID 39958070, 2025). "Pathogenic variants in ZMYND11 have been associated with intellectual disability, behavioral abnormalities, and seizures in humans." (PMID 32973871, 2020). "The chromatin reader ZMYND11 was first linked to a neurodevelopmental disorder as a candidate gene for the 10p15.3 microdeletion syndrome, characterized by symptoms including intellectual disability, language and motor delay, behavioral abnormalities, and seizures." (PMID 41279818, 2025). "However, the ZMYND11 gene in the region of the 10p15.3p13 duplication has previously been identified as a causative gene in intellectual disabilities, autism, epilepsy, hypotonia, and dysmorphism." (PMID 37251230, 2023). "Zmynd11 haploinsufficiency induces 10p15.3 deletion syndrome in human, and patients display neurological deficits including intellectual disability, behavioral abnormalities, and seizures." (PMID 40281637, 2025).
breast carcinoma (5 papers, 2021 to 2025). "The immunofluorescent staining results showed the co-localization of USP53 and ZMYND11, and Co-IP demonstrated their binding in breast cancer cells." (PMID 39044157, 2024). "USP53 induced deubiquitination and stabilization of ZMYND11, both of which were prognostic protective factors for breast cancer." (PMID 39044157, 2024). "A Study confirmed that overexpression of ZMYND11 significantly inhibited the proliferation of MDA-MB-231 breast cancer cells in vitro and the growth of transplanted tumors in nude mice." (PMID 39044157, 2024). "Bioinformatics analysis showed a positive correlation between the expression of USP53 and ZMYND11 in breast cancer tissues." (PMID 39044157, 2024). "The rescue experiments revealed that the anti-tumor role of USP53 in breast cancer cells was at least partially mediated by ZMYND11." (PMID 39044157, 2024). "Kaplan-Meier Plotter survival analysis showed that breast cancer patients with low expression of ZMYND11 had worse OS, RFS, distant metastasis-free survival (DMFS) and post-progression survival (PPS) than those with high expression." (PMID 39044157, 2024). "Both USP53 and ZMYND11 were prognostic protective factors for breast cancer." (PMID 39044157, 2024). "These evidences revealed that the anti-cancer function of USP53 may be mediated by ZMYND11 in breast cancer." (PMID 39044157, 2024). "ZMYND11 mediated the function of USP53 in breast cancer progression." (PMID 39044157, 2024). "In addition to CDKN1A, HEB and E2A co-occupy three TSG loci, APC, a haplo-insufficient tumor suppressor, ZMYND11 a chromatin reader and tumor suppressor in breast cancer and CUX1, a homeodomain transcription regulator and haploinsufficient tumor suppressor." (PMID 35401501, 2022). "The results showed that USP53 could significantly inhibit the growth of breast cancer grafts, decrease the proliferation activity of cancer cells, increase the number of apoptotic cells in the tumor, and still regulate the expression level of ZMYND11." (PMID 39044157, 2024). "Using CHX to inhibit protein synthesis in breast cancer cells, it was found that overexpression of USP53 delayed the degradation of ZMYND11, while knockdown of USP53 accelerated its degradation." (PMID 39044157, 2024). "The deficient binding between ZMYND11 and H3.3K36me3 or ablation of H3K36me3 marks will impair the antitumor effect of ZMYND11, giving rise to the invasive phenotype of MDA-MB 231 breast cancer cells and poorer outcomes of breast cancer patients." (PMID 34715919, 2021). "Additionally, ZMYND11 was found to interact with HNRNPA1 in the lung cancer cell line A549 and the breast cancer cell line MDA-MB-231, indicating that the association between ZMYND11 and HNRNPA1 might be common across different cancer types." (PMID 39341825, 2024). "Our results suggested that USP53 was low expressed in breast cancer and negatively correlated with TNM stage; USP53 suppressed proliferation and triggered apoptosis of breast cancer cells; USP53 inhibited breast cancer in vitro and in vivo by deubiquitinating ZMYND11." (PMID 39044157, 2024).
glioma (3 papers, 2017 to 2021). A benign or malignant brain and spinal cord tumor that arises from glial cells (astrocytes, oligodendrocytes, ependymal cells). "In contrast to IDH1-mutant gliomas, ATRX mutations associated with H3G34V, ZMYND11, EP300, or BRAF V600E were stable across the disease course in our study." (PMID 29084603, 2017). "On the contrary, circ_0008225 had been discovered to play a tumor suppressor role in glioma, which could inhibit the tumorigenesis of glioma through regulating the miR-8909/ZMYND11 network." (PMID 34150336, 2021).
schizophrenia (3 papers, 2024 to 2025). A major psychotic disorder characterized by abnormalities in the perception or expression of reality. "In our previous work, we successfully reprogrammed blood cells from a schizophrenia patient carrying a de novo mutation in the ZMYND11 gene into hiPSCs (Pat-Mut)." (PMID 40362679, 2025). "In ZMYND11, PTVs are associated with schizophrenia, DD and ASD, whereas missense variants are associated with DD." (PMID 40753099, 2025). "Four human iPSC lines, including two carrying a de novo ZMYND11 gene mutation associated with schizophrenia, were differentiated into hippocampal neural progenitor cells (NPCs), cultured either in monolayers or as 3D spheroids." (PMID 40362679, 2025).
Anxiety (2 papers, 2020 to 2025). Intense feelings of nervousness, tension, or panic often arise in response to interpersonal stresses. "For example, ZMYND11 variants were identified in mice with anxiety-like behavior." (PMID 32973871, 2020). "By contrast, wild-type and Zmynd11-cKO mice showed similar levels of exploration of open areas in an elevated plus maze, indicating that Zmynd11-cKO mice do not display an obvious anxiety phenotype." (PMID 41279818, 2025).
glioblastoma (2 papers, 2015 to 2021). The most malignant astrocytic tumor (WHO grade IV). "G34V/R mutations compromise ZMYND11 binding to the H3.3K36me3 peptide; however, a role for ZMYND11 has not been shown to date in any of the pediatric glioblastoma models or in chondroblastoma or giant cell tumors of bone." (PMID 25773741, 2015).
kidney cancer (2 papers, 2021 to 2024). Primary or metastatic malignant neoplasm involving the kidney. "This was consistent with the results of in vitro studies of ZMYND11 in brain glioma and kidney cancer." (PMID 39044157, 2024).
prostate carcinoma (2 papers, 2021 to 2024). A carcinoma that arises from epithelial cells of the prostate gland. "This indicates that ZMYND11 may serve as a potential prognostic marker to stratify intermediate-risk prostate cancer patients who may recur or progress to metastasis." (PMID 39341825, 2024). "We subsequently explored the impact of ZMYND11 on HNRNPA1 function in prostate oncogenesis by conducting forced co-expression of full-length ZMYND11 or a MYND-domain-deleted variant with HNRNPA1 in prostate cancer cells." (PMID 39341825, 2024). "Considering the consistent association between ZMYND11 expression status and prostate cancer prognosis, we investigated whether ZMYND11 levels could predict outcomes for low- and high-risk prostate cancer." (PMID 39341825, 2024). "Here, we report that ZMYND11 downregulation is prevalent across various cancers and profoundly correlates with poorer outcomes in prostate cancer patients." (PMID 39341825, 2024). "Collectively, these findings demonstrate that ZMYND11 suppresses aerobic glycolysis in prostate cancer cells by inhibiting HNRNPA1-dependent PKM splicing." (PMID 39341825, 2024). "Consistent with the knockdown assays, overexpression of ZMYND11 significantly suppressed colony formation, cell growth, migration, and invasion in the prostate cancer cell lines 22Rv1 and DU145." (PMID 39341825, 2024). "Taken together, these findings suggest a potential role for ZMYND11 in restricting prostate cancer progression to advanced stage and metastasis." (PMID 39341825, 2024). "The results consistently demonstrated that dampened ZMYND11 greatly stimulated colony formation, cell growth, migration, and invasion in the prostate cancer cell lines 22Rv1, DU145, and LNCaP." (PMID 39341825, 2024). "Taken together, upregulation of ZMYND11 reduces prostate cancer cell growth and metastasis both in vitro and in vivo." (PMID 39341825, 2024). "To examine the impact of upregulating ZMYND11 on prostate cancer cellular phenotypes and invasiveness, we conducted experiments in vitro and in xenograft mouse models in vivo." (PMID 39341825, 2024). "The findings indicated that xenograft prostate cancer tumors derived from 22Rv1 or DU145 cells with stable ZMYND11 silencing exhibited significantly enhanced growth compared to xenografts from control cells." (PMID 39341825, 2024). "As anticipated, ZMYND11 expression was significantly lower in murine prostate cancer tumors than in normal prostate glands." (PMID 39341825, 2024). "Our apoptosis assays further confirmed that ZMYND11 induces both early and late apoptosis in prostate cancer cells under stress, suggesting its role as a potential tumor suppressor." (PMID 39341825, 2024). "Knockdown of mouse Zmynd11 increased prostate cancer cell growth compared with the control group, suggesting that ZMYND11 suppresses tumor growth in the tumor microenvironment." (PMID 39341825, 2024). "To further elucidate the importance of ZMYND11 in prostate cancer, we compared its expression at both mRNA and protein levels in prostate tissue lysates from mice with Pbi–Cre–mediated deletion of Pten (Pten−/−), which develop indolent prostate cancer." (PMID 39341825, 2024). "Considering the pivotal role and clinical relevance of PRMT5 inhibitors in cancer progression, we explored whether PRMT5 inhibitors could serve as an effective therapeutic strategy for prostate cancer characterized by low ZMYND11 expression." (PMID 39341825, 2024). "Therefore, we conducted an immunoprecipitation experiment in prostate cancer LNCaP cells using an antibody against endogenous ZMYND11, followed by mass spectrometry (MS) analysis of the precipitated proteins." (PMID 39341825, 2024). "This suggests that ZMYND11 can induce early apoptosis in prostate cancer under stress conditions." (PMID 39341825, 2024).
prostate carcinoma (continued). "Remarkably, in a bioluminescent imaging (BLI)-based lung metastasis mouse model, established by tail vein injection of prostate cancer cells with stable ZMYND11 knockdown, treatment with PRMT5 inhibitors EPZ015666 or GSK3326595 substantially reduced lung metastasis." (PMID 39341825, 2024). "Finally, we confirmed that the expression of mutant SPOP prolonged the half-life of endogenous ZMYND11 in VCaP cells and upregulated ZMYND11 expression in other prostate cancer cells." (PMID 33531470, 2021). "Importantly, ZMYND11 was consistently downregulated in metastatic samples from several independent human prostate cancer clinical datasets, and its downregulation was notably correlated with high Gleason scores, advanced tumor stages, and elevated prostate-specific antigen (PSA) levels." (PMID 39341825, 2024). "We proceeded to examine the impact of ZMYND11 on prostate cancer tumor cellular phenotypes and invasiveness by conducting knockdown assays using lentivirus-mediated short hairpin RNA (shRNA) or synthetic small interfering RNA (siRNA) against ZMYND11 in several prostate cancer cell models." (PMID 39341825, 2024). "Additionally, the Y572 mutant negated the inhibitory effects of WT ZMYND11 on colony formation, cell growth, migration, and invasion in prostate cancer cells, indicating the essential role of the Y572 residue in mediating the tumor-suppressive function of ZMYND11." (PMID 39341825, 2024). "Altogether, our data elucidate the oncogenic and clinical impacts of HNRNPA1 on prostate cancer progression and demonstrate that ZMYND11 attenuates the oncogenic capabilities of HNRNPA1 through binding mediated by the MYND domain of ZMYND11." (PMID 39341825, 2024). "We first established mouse Zmynd11 knockdown in RM1 cell lines, which originated from the prostate cancer of C57BL/6J mice, and implanted these cells orthotopically into the prostate of C57BL/6J male mice." (PMID 39341825, 2024). "We discovered that ZMYND11 can physically interact with HNRNPA1 via its MYND domain, and this interaction is crucial for ZMYND11 to counteract HNRNPA1-induced aggressive phenotypes in prostate cancer cells." (PMID 39341825, 2024). "Given the correlation between ZMYND11 downregulation or HNRNPA1 upregulation and adverse outcomes in prostate cancer patients, we then examined whether these observations have relevant clinical implications." (PMID 39341825, 2024). "The results demonstrated a marked decrease in ZMYND11 protein levels in prostate cancer patient tumor samples compared to adjacent non-tumor tissues." (PMID 39341825, 2024). "Patients with low ZMYND11/high HNRNPA1 expression exhibited significantly shorter biochemical recurrence- or metastasis-free survival compared to those with high ZMYND11/low HNRNPA1 expression, indicating a synergistic prognostic effect of both genes on prostate cancer severity." (PMID 39341825, 2024). "Our results revealed a clear and frequent downregulation of ZMYND11 in non-epithelial cancers (brain, mesothelioma) and in multiple epithelial cancer types (cervix, colorectal, esophagus, stomach, pancreas, prostate), with a particularly significant reduction observed in prostate cancer." (PMID 39341825, 2024).
autosomal recessive spinocerebellar ataxia 30 (1 paper, 2025). "Among these, three were OMIM-annotated:ZMYND11 (associated with autosomal dominant intellectualdevelopmental disorder 30 [AD]), WDR37 (linked toneurooculo-cardiogenitourinary syndrome [AD]), PITRM1(implicated in autosomal recessive spinocerebellar ataxia 30[AR])." (PMID 40995453, 2025).
brain tumors (1 paper, 2022). "In addition, four other TSGenes are expressed at two- to eight-fold lower levels in T-ALL compared to brain tumors and/or B-ALL samples: NEDD4L, PLCB3, APC and ZMYND11." (PMID 35401501, 2022).
breast tumors (1 paper, 2019). "Some of these genes were amplified in breast tumors, like ZMYND11, which was found to be amplified in 28% of basal-like tumors." (PMID 30952871, 2019).
cervical dystonia (1 paper, 2025). "For ZMYND11, we observed a stop‐gain variant in a patient with infancy‐onset isolated generalized dystonia and a single amino acid duplication in a patient with cervical dystonia, tremor, and polyneuropathy (AAO unknown)." (PMID 40533913, 2025).